FOXP3 (forkhead box P3)
Diseases named in the same sentence as FOXP3 in open-access papers (continued):
Sharing a sentence is not in itself a finding about the gene and the disease.
autoimmune disease (continued). "Numerous studies conducted in recent years have shown that Treg lymphocytes, which express Foxp3, appear in the human body immediately after birth and lead to the development of many inflammatory and autoimmune diseases after they are depleted." (PMID 35207219, 2022). "Activation of Foxp3– T-conventional (T-conv) cells can precipitate autoimmune disease, whereas activation of Foxp3+ T-regulatory (T-reg) cells is essential to prevent autoimmune disease." (PMID 35693793, 2022). "Tregs (CD4+ CD25+ FoxP3+) mainly act as an inhibitory cell to prevent inflammatory pathology and autoimmune diseases." (PMID 35812246, 2022). "This is based on the observation that defects in Treg function have been reported in autoimmune diseases including T1D and MS and that experimental deletion of FOXP3 or reduced Treg function results in autoimmune disease in many model systems." (PMID 35773720, 2022). "It is reported that Treg cells are involved in the development of autoimmune diseases, and there are few reports on the changes in the number of Tr1 and Foxp3+Treg cells in NMOSD diseases." (PMID 35587519, 2022). "Potential immunosuppressive effects of TGF-β are accepted in autoimmune diseases used against most immune cells through the development and peripheral differentiation of Tregs and induced expression of FOXP3 in the context of T1D." (PMID 35725652, 2022). "This link between glycolysis and AS of Foxp3 reveals a new mechanism for regulating the induction and functions of Treg cells with perspectives in human health, particularly in the context of autoimmune diseases." (PMID 35406498, 2022). "Several studies showed that PD-L1 has an important effect on sustaining Tregs function in some autoimmune diseases, such as FOXP3 positive TILs and regulating signaling molecules that play a critical role in transforming naive T cells into Tregs." (PMID 36376881, 2022). "The role of CD4+CD25+Foxp3+ regulatory T (Treg) cells in abating the development of autoimmune diseases has been an area of intense study in recent years." (PMID 35563702, 2022). "FOXP3 presents with various immunosuppressive activities against intestinal inflammation, infections, tumors, autoimmune diseases, and allergies." (PMID 36039239, 2022). "Regulatory T cells (Treg cells, CD4 + CD25 Foxp3 +) are thought to be of particular importance to regulate Th17 cells and preventing autoimmune diseases." (PMID 35025939, 2022). "It has been shown that tregitopes have therapeutic effects on mouse models of autoimmune diseases through expansion of CD4 + CD25 + FOXP3 + Tregs37,41." (PMID 36418333, 2022). "While both isoforms are necessary for optimal Treg function, regulation of FOXP3 isoform ratios appears to alter the disease course in some autoimmune diseases." (PMID 36032083, 2022). "TET2 deletion leads to Foxp3 hypermethylation, impairs Treg cell differentiation and function, as well as autoimmune disease." (PMID 36056390, 2022). "The mutation of FOXP3 will lead to immune dysregulation, polyendocrinopathy, enteropathy, X-linked syndrome (IPEX), along with severe autoimmune diseases like enteropathy, type 1 diabetes (T1D), dermatitis and other autoimmune diseases." (PMID 35874688, 2022). "Further impairment of the stability of Foxp3 expression in Treg cells by a combined deficiency of CNS0 and CNS2 causes early onset lethal autoimmune disease comparable to that in Foxp3null mice." (PMID 36139121, 2022). "FOXP3+ Tregs are responsible for keeping immune tolerance, which can prevent allergic and other kinds of autoimmune diseases as well as inhibit the anti-tumor or anti-pathogen immune responses." (PMID 35874688, 2022). "Regulatory T cells, expressing CD25 and the transcription factor FoxP3, have immunomodulatory properties that help suppress inflammation and autoimmune diseases." (PMID 36148059, 2022).
autoimmune disease (continued). "In the broader context of autoimmune disease, multiple studies suggested that stability of Foxp3 expression is negatively affected by pro-inflammatory conditions." (PMID 36450783, 2022). "In addition, studies on the dysfunction of the Foxp3 transcription factor caused by the mutagenesis process have shown that it significantly affects disorders of the immune response as well as the development and progression of primary immunodeficiencies or autoimmune diseases." (PMID 35207219, 2022). "Together, these results prove that the maintenance of Foxp3 expression or Treg lineage stability is crucial for immune homeostasis and suppression of autoimmune diseases." (PMID 36139121, 2022). "Several authors including us have shown that the administration of IL-33 had a significant effect on the increased regulatory FoxP3+ cells, which suppress autoimmune diseases including the MLD–STZ diabetes." (PMID 34803672, 2021). "The balance between Foxp3+ Tregs and Th17 cells is crucial in autoimmune diseases, including asthma." (PMID 33806085, 2021). "Treg cells, define as CD4+CD25+Foxp3+, exert their immunosuppressive effect in various autoimmune diseases." (PMID 34702288, 2021). "The important role of Foxp3+ Treg cells is shown when patients lack the gene, Foxp3, which results in the development of a fatal autoimmune disease." (PMID 33937944, 2021). "There are reports on experimental models of allergic and autoimmune diseases showing augmented frequencies of either CD4+CD25+Foxp3+ and CD4+LAP+ iTregs in spleen and draining lymph nodes of tolerant mice." (PMID 35919733, 2021). "This region is also bound by STAT5, and cooperatively with Il-2 enables Foxp3 induction in Tregs precursors, while its depletion together with Aire resulted in a worsened autoimmune disease." (PMID 34281195, 2021). "Recent evidence in a mouse model of autoimmune diseases indicates that female sex hormone (17β-estradiol-E2) influences the expression of FoxP3 and Treg number and function." (PMID 33746959, 2021). "For example, in multiple sclerosis and autoimmune disease, differential methylation of the X-chromosome gene, Foxp3, has been identified in T lymphocytes; possibly resulting from X-chromosome imprinting." (PMID 33927243, 2021). "The absence of OX40 and CD30 co-stimulatory signals prevents CD4 T cell-driven autoimmune disease and anti-tumor CD8 T cell responses can be achieved in Foxp3-deficient mice." (PMID 33527196, 2021). "Under noninflammatory conditions, Cd25Y129H mice harbored substantially lower numbers of peripheral Treg cells with stable Foxp3 expression that prevented the development of spontaneous autoimmune disease." (PMID 33408345, 2021). "Genes relating to certain subsets of T cells that are often connected with autoimmune diseases such as Tregs (FOXP3, CD25) and TH17 (IL-17, RORC) were decreased in gene lists." (PMID 34164359, 2021). "CD4+Foxp3+ Tregs which serve as a small subset of T cells play an important role in maintaining immunological tolerance and preventing autoimmune diseases in psoriasis." (PMID 32908937, 2020). "Given this potential regulatory rheostat relationship between FOXP3 and miR-31, it is interesting that miR-31 is dysregulated in several autoimmune diseases such as inflammatory bowel disease (IBD) or Crohn's disease and Kawasaki disease." (PMID 33072063, 2020). "Mutation of the genotype of rs3761548 mostly affects the expression and activity of FOXP3 protein, which was further involved in many autoimmune diseases including rheumatoid arthritis, allergic rhinitis, and autoimmune thyroid disease." (PMID 33317466, 2020). "An ideal strategy for antigen-specific immune suppression is to convert not only naïve but also effector/memory Tconv cells mediating autoimmune disease into functionally stable FoxP3+ Treg cells in vivo and in vitro." (PMID 32367041, 2020). "In the context of autoimmune diseases both FOXP3+ Tregs and Tr1 cells have been tested in clinical trials." (PMID 33133064, 2020).
autoimmune disease (continued). "CD4+Foxp3+ T cells were increased in SLE patients compared with organ-specific autoimmune disease controls or healthy controls." (PMID 32317002, 2020). "Consistent with genetic studies in human and mouse, reduction in numbers and functions of Foxp3+ Tregs had been reported as a contributing factor for a variety of autoimmune diseases." (PMID 32269069, 2020). "In humans, this is mirrored in IPEX patients who lack FOXP3 and Treg, and the early development of autoimmune disease in IPEX confirms that Treg are also essential in humans." (PMID 33072063, 2020). "The ability of LSECs to promote induction of FoxP3+ Tregs, prompted the development of NPs to deliver Ags to LSECs for autoimmune disease treatment." (PMID 33133064, 2020). "Recently, a population of CD4+CD39+Foxp3+ T cells was identified as having a regulatory function in the autoimmune disease model." (PMID 30622237, 2019). "Recent studies showed that the increase of IL-10-producing Foxp3+Tregs was accompanied with disease remission in several different systematic autoimmune diseases, such as experimental autoimmune encephalomyelitis, diabetes, and arthritis." (PMID 31380412, 2019). "In patients with active autoimmune disease, chronic immune activation promotes the accumulation of PD-1+ CD25lowFOXP3+ Tregs as conventional activated FOXP3+HELIOS+ CD25hi Tregs proliferate in an attempt to regulate autoreactive Teff hyperactivity." (PMID 31781109, 2019). "Some pre-clinical studies have been carried out using adoptive therapy with FoxP3 transduced cells, particularly in autoimmune disease and in transplant rejection." (PMID 30842776, 2019). "Since Helios+ Foxp3+ CD4+ (Helios+) Treg cells are involved in the regulation of multiple autoimmune diseases, they can potentially improve the expression of various Treg-related molecules and the function of induced Treg cells." (PMID 30974919, 2019). "There are several reports regarding the relevance of IL-17-producing FOXP3+ T cells in autoimmune diseases." (PMID 31354747, 2019). "The balance between FOXP3+ Treg cells and Th17 cells is considered an important target for treatment of autoimmune diseases and cancers." (PMID 31815635, 2019). "While imbalance of FOXP3+Tregs has been widely reported in autoimmune diseases such as allergic rhinitis and Graves’ disease, the role of FOXP3 in tumorigenesis has long been controversial." (PMID 30782783, 2019). "Human research has also shown that a genetic defect of the FoxP3 gene can prevent the Treg cells development, leading to ranges of autoimmune diseases and severe allergies." (PMID 30693029, 2019). "It is well-known that CD39 Treg cells play an essential role in constraining pathogenic Th17 cells and preventing autoimmune disease, potentially involving both the IL-10 and TGF-β produced by Foxp3+CD39+ and Foxp3−CD39+ cells, respectively." (PMID 31258540, 2019). "A correlation between infection and increased ubiquitination of Foxp3 has also been reported during autoimmune diseases such as psoriasis." (PMID 32117202, 2019). "Such Th1-like Treg cells producing IFN-gamma (but maintaining Foxp3 expression) have been reported to be present at an increased frequency in both mouse models and patients with autoimmune diseases such as type 1 diabetes or multiple sclerosis." (PMID 30936873, 2019). "Scurfy mice have a spontaneous mutation of Foxp3, develop hyper-responsive CD4 + T cells and a progressive and fatal autoimmune disease." (PMID 30067137, 2019). "The dysfunction of FOXP3-positive regulatory T cells (Tregs) plays a key role in the pathogenesis of autoimmune diseases, including type 1 diabetes (T1D)." (PMID 30723474, 2019). "The effect of micelle-delivered curcumin was tested on the expansion of TCD4+CD25+FOXP3+CD127- cells (Tregs) as crucial regulating cells in repressing auto-aggressive responses in autoimmune diseases." (PMID 31338010, 2019).
autoimmune disease (continued). "We investigated the classical CD4+CD25+Foxp3+ Treg phenotype which was widely used in autoimmune diseases, but also supplied novel evidence of Treg subpopulations in different clinical stages of HT and their associations with clinical features." (PMID 31214258, 2019). "As an autoimmune disease, MG is characterized by the overproduction of AChR antibodies; the disequilibrium of B cells and Foxp3+ CD4+ Treg cells is involved in the overproduction of AChR antibodies." (PMID 30483222, 2018). "The key transcription factors of T helper cell subpopulations, including T-bet, GATA3, RORγt, and Foxp3 are involved in various autoimmune diseases." (PMID 30254507, 2018). "Regulatory T cells (Tregs) expressing the transcription factor FOXP3 are crucial mediators of self-tolerance, preventing autoimmune diseases but possibly hampering tumor rejection." (PMID 29730990, 2018). "Regulatory T cells (CD4+/CD25+/FoxP3+) are a subpopulation of T cells that modulate the immune system, maintain tolerance to self-antigens, and prevent autoimmune disease." (PMID 29973247, 2018). "Induced Tregs and FOXP3 expression after treatment with ATRA alone have been reported in another autoimmune disease like type 1 diabetes." (PMID 29854846, 2018). "A critical role for miRNA in Treg function was initially discovered when both Dicer and Drosha knockout (KO) mice were found to develop a fatal autoimmune disease phenotypically similar to Foxp3 KO mice." (PMID 29445371, 2018). "Hhph-1 showed higher Foxp3 delivery into the nucleus compared with Hph-1 for converting CD4+ T cells to suppressor cells to inhibit autoimmune diseases in mice." (PMID 29518031, 2018). "The differentiation of Tregs is modulated by the expression of the lineage-specific transcription factor forkhead box P3 (Foxp3), which can suppress autoimmune diseases in normal individuals." (PMID 29056830, 2017). "FOXP3+ regulatory T cells (Tregs) represent a promising platform for effective adoptive immunotherapy of chronic inflammatory disease, including autoimmune diseases such as multiple sclerosis." (PMID 29312311, 2017). "The CD4+CD25+Foxp3+ regulatory T (Treg) cells, specified by the transcription factor forkhead box P3 (Foxp3), which mainly regulate peripheral T cell tolerance, are critically involved in the pathogenesis of autoimmune diseases." (PMID 28177888, 2017). "Tregs are a population of T cells characterized by the expression of CD25 (IL-2Ra) and the transcription factor Foxp3, and their general role has been demonstrated as immunosuppressive in various experimental settings of autoimmune diseases." (PMID 28280495, 2017). "The impaired function of CD4+CD25+Foxp3+ Tregs has been confirmed to contribute to the pathogenesis of autoimmune diseases including AA." (PMID 28683082, 2017). "These mice develop a fatal early-onset autoimmune disease with defective maintenance of stable Foxp3 expression and suppressive capacity in Treg cells." (PMID 28621313, 2017). "IFN-γ-producing FoxP3+ Tregs were detected in the context of graft-versus-host disease, in Listeria monocytogenes infection in mice and also in human autoimmune disease." (PMID 28536578, 2017). "For example, ex vivo expanded polyclonal CD4+CD25+FoxP3+ Tregs are successfully used in hematopoietic stem cell transplants to prevent graft vs host disease are also evaluated in the treatment of autoimmune disease." (PMID 29225598, 2017). "An increased frequency of CD25low FOXP3+ Tregs has now been reported in a growing number autoimmune diseases, including SLE, rheumatoid arthritis and multiple sclerosis." (PMID 28747257, 2017). "In contrast, high salt levels have been shown to impair the functionality and development of regulatory forkhead box P3 (Foxp3)+ T cells (Tregs), which play a key role in self-tolerance and are dysregulated in autoimmune diseases." (PMID 26921211, 2017).
autoimmune disease (continued). "More studies are required to gain an improved understanding of how the subimmunogenic application of antigens for the efficient and stable induction of Foxp3+Treg cells can be best achieved in human autoimmune diseases." (PMID 26975663, 2016). "Accumulating evidence underlines that milk is a complex signalling and epigenetic imprinting network that promotes stable FoxP3 expression and long-lasting Treg differentiation, crucial postnatal events preventing atopic and autoimmune diseases." (PMID 27175277, 2016). "CD4+/FOXP3+ Tregs are a subset of suppressive T cells that are crucial to the development and maintenance of self-tolerance that have been shown to prevent autoimmune disease." (PMID 27310015, 2016). "Understanding the positive and negative regulation of Foxp3 is critically important in controlling Treg cell-regulated immune responses, including those involved in autoimmune diseases, allergies, organ transplantation and cancer." (PMID 26892542, 2016). "This population was described as being involved in the pathogenesis of different autoimmune diseases, due to harboring an elevated frequency of autoreactive lymphocytes and being more prone to lose Foxp3 expression under inflammatory settings." (PMID 27980781, 2016). "FoxP3+ Regulatory T cells (Treg) which are essential for maintaining peripheral tolerance, preventing autoimmune diseases and limiting chronic inflammatory diseases also dampen proinflammatory T cells that include T helper 17 (Th17) cells." (PMID 26751584, 2016). "CD4+CD25+Foxp3+ regulatory T cells (Tregs) play an indispensable role in the immune system as they are involved in the prevention of autoimmune disease, allergies and infection-induced organ pathology by suppression of other immune cells." (PMID 26886923, 2016). "FOXP3 T regulatory cells are required to prevent autoimmune disease but also prevent clearance of some chronic infections." (PMID 25969456, 2016). "Several studies have demonstrated increased percentages of FOXP3+ CD4+ T cells in the periphery and reduced organ-specific autoimmune disease susceptibility, including T1D in the NOD model." (PMID 26438525, 2015). "Recently, the imbalanced development and function of IL-17-producing Th17 and Foxp3+ Treg cells have been demonstrated to play an important role in autoimmune diseases, including IBD." (PMID 26583087, 2015). "FOXP3 (forkhead box P3), also believed to have involvement in some autoimmune diseases, is a key transcription factor controlling activation of regulatory T cells (Treg cells)." (PMID 25763008, 2015). "Here, we review recent findings on the regulation of FOXP3 activity in Treg cells and also discuss gender difference in the determination of Treg cell function in autoimmune diseases." (PMID 26441996, 2015). "In contrast to thymic-derived CD4+CD25+FOXP3+ Tregs, their origin and their role in the pathophysiology of autoimmune diseases (AIDs) are less understood." (PMID 25926835, 2015). "Mice null FoxP3-/- developed devastating autoimmune disease, marked by splenomegaly, lymphadenopathy, insulitis, severe skin inflammation, delayed body development and less survival." (PMID 26115356, 2015). "Later rs3761548 AA genotype was confirmed to be the lowest FOXP3 producing genotype and suggested its role in fewer Treg cells and/or weaker immune suppressive function in other autoimmune diseases." (PMID 26257775, 2015). "Foxp3+ Treg cells can suppress the activation of Th17 cells and other effector T cell subsets as well as the development of certain autoimmune diseases, including CIA." (PMID 25928901, 2015). "Lymphocytes with regulatory properties such as Foxp3+CD25+CD4+ regulatory T cells are of crucial interest as they play essential role in maintaining peripheral tolerance preventing autoimmune diseases." (PMID 25541968, 2014).